MTOR (mechanistic target of rapamycin kinase)
Diseases named in the same sentence as MTOR in open-access papers (continued):
Sharing a sentence is not in itself a finding about the gene and the disease.
glioma (continued). "The molecular characteristics of individual tumors, such as the level of activated PTEN, PI3K, AKT, mTOR, and ERK, are important prognostic factors for patients with glioma." (PMID 27683117, 2016). "Inhibition of autophagy in glioblastoma cells, using a dual pI3K/ mTOR inhibitor (NVP-BEZ235), led to increased radiosensitization in both in vitro and in vivo glioma models." (PMID 27043632, 2016). "This compound was observed to induce apoptosis in the glioma cells by inducing the caspase dependent apoptotic pathways via ROS and downregulating the PI3K/AKT/mTOR pathway." (PMID 27380262, 2016). "Combination treatment with WA and TMZ resulted in resensitization of MGMT mediated TMZ-resistance by Akt/mTOR pathway inhibitory modulation, which probably enhance the autophagic cell death in PTEN-null U87 glioma cells." (PMID 26830677, 2016). "It has been demonstrated that Notch-1 promoted proliferation and survival of glioma cells through EGFR/Mcl-1 and mTOR signaling." (PMID 26824182, 2016). "Evidence has shown that CRNDE can promote glioma cell growth and invasion through mTOR signaling, thereby highlighting the potential of CRNDE as a novel therapeutic target for the treatment of glioma." (PMID 27043545, 2016). "Both treatment with the mTOR inhibitor INK128 and YB-1 knockdown decrease the migration and invasiveness of glioma cells in vitro." (PMID 28983350, 2015). "Moreover, in the present study, changes in mTOR/p70S6K1 signaling pathway occurred in U87 and U251 glioma cells following GSK-3β overexpression, suggesting that this signaling pathway may play an important role in the GSK-3β-inhibited glioma development events." (PMID 26388612, 2015). "In our study, miR-199a-3p suppresses glioma cellular growth and proliferation via regulating AKT/mTOR signaling pathway." (PMID 25854175, 2015). "In human glioma cells, activation of HIF-1α, a positive downstream target of mTOR, enhances CD133+ glioma-derived cancer stem cell expansion by increasing self-renewal activity and inhibiting cell differentiation." (PMID 25815458, 2015). "Using glioma cells, it was shown that NVP-BEZ235 specifically inhibited PI3K/mTOR signaling; an observation supported by suppressed activity of AKT, and S6K1." (PMID 25221930, 2014). "Two tumor suppressors in the PI3K-mTOR pathway altered in the majority of human gliomas, PI3K regulatory subunit pi3kr1 and the tsc1 repressor of mTOR, were decreased in expression level in the Tg(flk1:RFP)is18 tumors." (PMID 25485542, 2014). "In conclusion, the main finding of this study is the observation that mTOR inhibition by RAPA and RAD prevents microglial polarization towards an M2 phenotype in in vitro models of both early- and late-stage glioma." (PMID 25051975, 2014). "In contrast, starved and AZD 8055-treated control MEFs and U87-MG glioma cell lysates showed dephosphorylation of Ser-757 or a corresponding shift in the mobility of total ULK1, consistent with an mTOR-mediated response." (PMID 23762328, 2013). "Therapy-resistant PTEN-mutant gliomas fail to undergo significant cell death in response to PI3K and mTOR inhibitors; however, treatment with a dual PI3K-mTOR inhibitor, PI-103, led to an induction of autophagy." (PMID 24287492, 2013). "Here, we show in vitro data demonstrating that the most effective inhibition of Akt and mTOR activity in both PTEN-intact and PTEN-null primary glioma cell cultures is obtained when using both inhibitors in combination." (PMID 21267448, 2011). "Compound 58 displayed potent biochemical activity against p110α (Ki = 1nM) and mTOR (IC50 = 15nM), and potently inhibited U87 glioma tumour cell proliferation (IC50 = 7nM)." (PMID 21649578, 2011). "Having established that perifosine and CCI-779 combine to completely inhibit the PI3K/mTOR pathway in glioma cultures, we next wanted to investigate if the two treatments maintained their synergy when used to treat PDGF-B driven gliomas in vivo." (PMID 21267448, 2011).
glioma (continued). "As mTOR inhibitor blocks STAT activation and glial differentiation and since STAT3 inhibitors induce apoptosis in glioma cells, we determined the status of STAT3 activation in Iripallidal treated cells." (PMID 20576128, 2010). "Since Iripallidal inhibits mTOR and STAT3 activation in glioma cells we investigated its ability to regulate telomerase activity." (PMID 20576128, 2010). "Similarly, the monoclonal antibody C107, an IgG directed to the C-terminus of GRP78, has been shown to suppress glioma cell proliferation and induce apoptosis by broadly inhibiting the PI3K/AKT/mTOR signaling pathway." (PMID 40002794, 2025). "Furthermore, triptolide induces glioma cell growth via autophagy through ROS/JNK activation and inhibition of the AKT/mTOR signaling pathway." (PMID 40490812, 2025). "In vitro experiments substantiated the role of TREM1 in the proliferative and invasive processes of gliomas, demonstrating that TREM1 exerts its biological functions through the TLR4/PI3K/AKT/mTOR signaling axis, thereby facilitating the PMT transformation of glioma cells." (PMID 41394801, 2025). "Metformin may affect the behavior of glioma stem cells by activating AMPK and inhibiting the phosphorylation of mTOR and STAT3." (PMID 39944825, 2025). "Integrating molecular glioma classification with mechanisms of epileptogenesis (including particular mechanisms involved in GAE such as IDH and mTOR pathway alterations, glutamatergic dysregulation, and cancer neuroscience) is crucial for improving diagnosis, prognostication, and treatment." (PMID 41074169, 2025). "Additionally, metformin affects glioma stem cells by inhibiting key pathways, including STAT3, mTOR, and AKT, and altering the tumor microenvironment." (PMID 39944825, 2025). "Interestingly, we observed the upregulation of RASD1, a gene that inhibits glioma cell migration and invasion by deactivating the AKT/mTOR signaling pathway." (PMID 39874307, 2025). "The common enrichment of these two lncRNA interaction networks in key pathways including “Glioma” and “PI3K-Akt/mTOR” suggests that they may drive malignant progression in LGG through coordinated regulation of similar molecular networks." (PMID 41373831, 2025). "In glioma, YBX1 may act as an important activator of the mTOR signaling pathway and mediate the YBX1/CCT4/mLST8/mTOR axis to promote the growth of glioblastomas." (PMID 38849679, 2024). "Our results suggested that YANK2, which is independent of mTOR, directly phosphorylates the T389 site of p70S6K to increase the growth of glioma." (PMID 38714727, 2024). "Conversely, TPX2 downregulation could impede colon cancer and glioma cell proliferation and migration through PI3K/AKT/mTOR pathways." (PMID 38315450, 2024). "Furthermore, knockdown of CLK1 In glioma cells (GL261) increased aerobic glycolysis and expression of HIF-1α via the AMPK/mTOR signaling pathway." (PMID 39742274, 2024). "Besides, it has been reported to induce apoptosis in glioma cells in vitro and in vivo through the regulation of the AKT/mTOR pathway." (PMID 38466979, 2024). "Studies have shown that the angiogenesis and invasion of glioma cells can be repressed by silencing LncRNA HULC through inhibiting glioma cell proliferation, which induces apoptosis and blocks G1/S cell cycle through PI3K/Akt/mTOR signaling pathway." (PMID 39651612, 2024). "AKT positively correlated with LC3, PI3K, PTEN, ULK1, VPS34, mTOR, Beclin1, UVRAG, miR-7, miR-30, miR-204, miR-374, miR-126 and miR-21 weakly correlated with AKT and miR-30 in high-grade glioma, providing further insights into the autophagy pathway within our population." (PMID 39348350, 2024). "Taken together, we found a new mTOR-independent p70S6K activation pathway, Fyn-YANK2-p70S6K, which promotes glioma growth, and YANK2 is a potential oncogene and serves as a novel therapeutic target for glioma." (PMID 38714727, 2024).
glioma (continued). "Additionally, we evaluated the PI3K/AKT/mTOR pathway, focusing on the AKT gene, which exhibited significant upregulation in high-grade gliomas compared to low-grade ones, suggesting increased tumor proliferation in the malignant stage." (PMID 39348350, 2024). "In 39 glioma cases, we assessed the protein expression of autophagy markers LC3B, SQSTM1/p62, and DRAM by immunohistochemistry (IHC) and the mRNA expression of the autophagy genes PTEN, PI3K, AKT, mTOR, ULK1, ULK2, UVRAG, Beclin 1, and VPS34 using RT-qPCR." (PMID 38203743, 2024). "In grade 3 gliomas, a significant, strong, positive correlation was observed between PI3K and mTOR, ULK2, UVRAG; mTOR and PTEN; PTEN and m-TOR, ULK 2, UVRAG; mTOR and PI3K, PTEN; ULK1 and ULK2, UVRAG; ULK 2 and PI3K, PTEN, ULK 1, UVRAG, VPS34; UVRAG and PI3K, PTEN, ULK1, ULK2, VPS34." (PMID 38203743, 2024). "Moreover, in glioma cells, NAC also induced AMT-reduced P62 expression, decreased the LC3 II/LC3 I ratio, and reversed AMT-inhibited AKT/ mTOR phosphorylation." (PMID 39548081, 2024). "In addition, it has been demonstrated that M2 macrophage-sourced exosomal miR-15a and miR-92a contribute to inhibiting glioma invasion and migration via the PI3K/AKT/mTOR pathway." (PMID 37174088, 2023). "Furthermore, hirudin inhibited glioma growth and induced changes in autophagy in cell‐derived xenograft (CDX) nude mice, with a decrease in mTOR activity and activation of LC3‐II." (PMID 37539490, 2023). "Due to the prominent role of PI3K/Akt/mTOR and MEK/ERK signaling pathways in the phosphorylation of FOXO3a, inhibiting these two signaling pathways can be an promising method for differentiation therapy against high-grade gliomas, especially GBM." (PMID 37821870, 2023). "NLGN3 was shown to activate Akt-mTOR, Erk-MAPK, and other signaling cascades in glioma cells." (PMID 37880221, 2023). "Other studies found that ULBP2 was negatively regulated by miR-873 to inhibit proliferation, invasion, and migration of cervical cancer cells and ULBP2 was bond by miR-6071 to inhibit glioma cell proliferation and invasion and promote cell apoptosis through PI3K/Akt/mTOR pathway." (PMID 36742322, 2023). "It has been shown that glioma progenitor cells enhance mTOR signaling in microglia but not in BMDMs via the PI3K (phosphatidylinositol 3 kinase)/Akt (Protein Kinase B) axis." (PMID 37700840, 2023). "Several signaling pathways such as the ß-catenin or the mTOR pathway have been shown to be among the downstream signaling pathways activated by PTPRZ1, and this activation occurs in glioma cells as well as in the stimulation of oligodendrocyte progenitor cell growth." (PMID 38275375, 2023). "Mechanistically, hirudin activated LC3‐II but not Caspase‐3 to induce the autophagic death of glioma cells by decreasing the phosphorylation of mTOR and its downstream substrates ULK1, P70S6K and 4EBP1." (PMID 37539490, 2023). "HSV-1 was found to induce autophagy in glioma cells without a significant increase in the expression of the pro-autophagic protein Beclin-1 and an increase in the phosphorylation of mTOR and Akt." (PMID 37026095, 2023). "In glioma, miR-15a/16 depletion activated tumor-infiltrating CD8+ T cells via the mammalian target of rapamycin (mTOR) signaling pathway, as indicated by the downregulation of PD-1 expression and the increase of the anti-tumor factor IFN-γ production in T cells." (PMID 37275876, 2023). "FDX1 promoted glioma cell proliferation and migration, possibly through the PI3K/AKT/mTOR pathway." (PMID 37515314, 2023). "In addition to the role played by the mGluR1 in the activation of PI3K/AKT/mTOR in glioma, MAPK and PI3K pathways are activated by mGluR2/3 in glioma." (PMID 36817470, 2023).
glioma (continued). "In addition, the antiproliferation effect of gartanin in T98G glioma cells is most likely modulated by autophagy, which is regulated by the PI3K/AKT/mTOR signaling pathway." (PMID 36211598, 2022). "Given that Akt/mTOR signaling pathway is a pivotal mediator for NSC expansion and plays an important role in counteracting oxidative stress in macrophage and glioma cells, we then posited that Akt/mTOR signaling pathway was involved in regulating NSC proliferation resulting from oxidative stress." (PMID 35265266, 2022). "In glioma cells, STAT6 negatively regulated HIF-1α expression via mTOR/S6K/S6 axis." (PMID 35600336, 2022). "The reason why N‐acetylgalactosaminyltransferase 2 (GALNT2) was closely associated with the migration and invasion of glioma cells is that GALNT2 facilitated the malignant features of gliomas by affecting the O‐glycosylation, EGFR phosphorylation, and subsequently the downstream PI3K/Akt/mTOR axis." (PMID 37786890, 2022). "LINC01857 acts as an oncogene that promotes BC development by promoting H3K27Ac and CREB1 transcription, regulates glioma progression by modulating the miR-1281/TRIM65 pathway, promotes the proliferation of cancer cells by activating the PI3K/mTOR pathway, and facilitates the EMT process in DLBCL." (PMID 36168326, 2022). "Agents targeting PDGFRA‐alterations, such as dasatinib, failed to exert any effect in clinical trials in glioma patients, but there are some promising data regarding the potential efficacy of combinations with mTOR inhibitors." (PMID 35545820, 2022). "Taken together, our results show that activation of autophagy does not account for the cytoprotective effects of mTOR inhibition in our in vitro model of the glioma microenvironment." (PMID 36202792, 2022). "On the other hand, in gliomas, Akt but not mTOR regulates ATP binding cassette transporters (ABCG2) activity, which is referred to as stemness hallmark." (PMID 36226253, 2022). "Further study found that Spi exhibits significant anti-proliferative effects on glioma cells in both in vitro and in vivo models by decreasing the expression of PI3K/AKT/mammalian target of rapamycin (mTOR) and increasing the expression of miR-34a and miR-125b." (PMID 36532760, 2022). "Microglia can regulate STAT 3 and NF-κB activity via mTOR, promote the immunosuppressive microglia phenotype to promote glioma immune escape, and upregulate their own IL-6 secretion via TLR4 as a mitogen for glioma stem cells." (PMID 36497459, 2022). "As observed in other gliomas, such as subependymal giant cell astrocytoma (SEGA), in which stopping the mammalian target of rapamycin mTOR inhibitors (mTORi) results in inevitable tumor regrowth, after the discontinuation of BRAFi, up to 75% of patients experienced rapid progression in a few weeks." (PMID 35681673, 2022). "The energy demands of gliomas alter their microenvironment quality, thereby inducing heterogeneity and plasticity change of stromal and immune cells via the PI3K/AKT/mTOR pathway, which ultimately results in epigenetic modifications that facilitates tumor growth." (PMID 35392088, 2022). "In glioma studies, multiple evidences revealed that the activation of PI3K/AKT pathway could enhance cell proliferation in a mTOR dependent or independent way 16-18." (PMID 35003348, 2021).
glioma (continued). "In addition, an inhibition of the key signaling pathways such as NF-κB, JAK/STAT, MAPK, PI3K/Akt/mTOR, and TLRs, which are activated during neuroinflammation and have an oncogenic role in glioblastoma (GBM), can exert more pronounced anti-glioma effects." (PMID 34439380, 2021). "Consistently, GBM-exo, LINC00470 overexpression or miR-580-3p knockdown could activate PI3K/AKT/mTOR signaling pathway, supporting the regulatory role of LINC00470 on PI3K/AKT/mTOR signaling pathway in glioma cells." (PMID 33663509, 2021). "Interestingly, IL-13Rα2-depleted-U87 glioma cells exhibited a marked decrease in the expression of p-PI3K and its downstream target gene p-Akt and p-mTOR, thus restricting tumor growth." (PMID 34439380, 2021). "Overactivation of mTOR and MEK is also predominant in gliomas." (PMID 34359780, 2021). "Both BYSL and RIOK2 positively regulated AKT/mTOR signaling, which might be responsible for the promoting effects of BYSL on human glioma growth." (PMID 33628587, 2021). "Indeed, the overexpression of BYSL caused a significant increase in the protein levels of RIOK2, AKT, PARS40, mTOR, P70S6K, and S6 in glioma cells." (PMID 33628587, 2021). "Additionally, TCM celastrol suppresses the viability of human U251, U87‐MG and C6 glioma cells by modulating ROS/JNK and Akt/mTOR signalling pathways, indicating the potentially therapeutic effect of TCM celastrol on gliomas." (PMID 34632655, 2021). "LINC00470 in GDE could competitively bind to miR-580-3p in glioma cells to modify WEE1 expression and activate the PI3K/AKT/mTOR pathway, thus suppressing autophagy and strengthening the proliferation of glioma cells." (PMID 34887381, 2021). "Overexpression of RASD1 inhibited glioma expansion and inactivated the AKT/mTOR pathway." (PMID 33706799, 2021). "Studies have found that downregulating the CLK1 gene in glioma GL261 cells can inhibit mitochondrial function, reduce AMPK phosphorylation levels, activate the mTOR signaling pathway, promote the upregulation of HIF-1α in tumor cells, and enhance the sensitivity of GL261 cells to chemotherapy drugs." (PMID 34568328, 2021). "Our enrichment plots data suggest that PYGL may induce glioma proliferation through up-regulation of mTORC1 signaling, PI3K/AKT/mTOR signaling, KRAS signaling up, and angiogenesis pathway." (PMID 34177761, 2021). "For example, CEP55 promoted the migration, invasion, and neurosphere formation of the glioma cell, promoted epithelial-mesenchymal transition in renal cell carcinoma through the PI3K/AKT/mTOR pathway, and promoted migration and invasion of esophageal squamous cell carcinoma via the PI3K/AKT pathway." (PMID 34055036, 2021). "Through the mTOR pathway, targeting NLGN3 secretion promoted the proliferation of gliomas." (PMID 33015162, 2020). "In conclusion, our data provide evidence that MOX can induce autophagy in glioma cells, and autophagy could increase MOX-induced apoptosis through inhibiting the AKT/mTOR signalling pathway." (PMID 32913473, 2020). "Moreover, preclinical investigations using selected mTOR and PI3K inhibitors, have shown only a moderate efficacy against gliomas." (PMID 32517694, 2020). "In glioma, miR-92a has been identified to accelerate proliferation, cell survival, and metastasis through regulating BCL2L11, cadherin 1 (CDH1, also known as E-cadherin) and the Akt/mechanistic target of rapamycin kinase (mTOR) signaling." (PMID 33066509, 2020). "However, PI-103, a dual functional mTOR and PI3K inhibitor, did show beneficial anti-proliferative effects in preclinical glioma models, by suppressing the Akt activation often found with mTOR blockers." (PMID 32517694, 2020). "Exposure of human high-grade glioma cells to soluble neuroligin 3 secreted by active neurons results in increased phosphorylation of eukaryotic translation initiation factor 4E-binding protein 1 (4E-BP1), which is an mTOR downstream effector." (PMID 33281551, 2020).